CIITA (class II major histocompatibility complex transactivator)
Diseases named in the same sentence as CIITA in open-access papers (continued):
Sharing a sentence is not in itself a finding about the gene and the disease.
ovarian carcinoma (6 papers, 2015 to 2023). A malignant neoplasm originating from the surface ovarian epithelium. "The Indian Cohort showed MUC16, MUC4, and CIITA to be most mutated and carry CNV in the same genes apart from MYC, which is known to be amplified in most cancers, including ovarian cancer." (PMID 37091785, 2023). "Overall, the IL-27-induced gene expression pattern and the employed STAT1/IRF/CIITA signalling pathways identified here in IEC resemble that described for IFN-γ in different cell types such as hepatocytes or ovarian cancer cells." (PMID 37818353, 2023). "After CIITA-expressing ovarian cancer cell lines were pulsed with NY-ESO-1157–170 peptide, they were efficiently recognized by both NTR-CD4 as well as TR-CD4." (PMID 26447332, 2015). "Hence, the frequency and hotspot mutations in the genes NCOR2, CIITA, MUC4, and MUC16 point towards their role in driving oncogenesis in all ovarian cancer histotypes." (PMID 37091785, 2023). "Two DP4+ ovarian cancer cell lines (OV2774 and OVCAR-5) were transduced with a self-inactivating bicistronic retroviral vector encoding class II transactivator (CIITA), which induced cell surface MHC-II expression, and NY-ESO-1 or control human sperm protein 17 (Sp17) gene." (PMID 26447332, 2015). "IRF4, GATA4, GATA3, CIITA, and MYH11 were involved in the immune regulatory network, indicating that these five transcription factors might play a role in the immune microenvironment of ovarian cancer." (PMID 34109184, 2021).
glioma (5 papers, 2021 to 2024). A benign or malignant brain and spinal cord tumor that arises from glial cells (astrocytes, oligodendrocytes, ependymal cells). "The univariate Cox regression showed that the expression levels of PD-L2, TIM3, CD80, CD86, CD155, and CIITA were risk factors for glioma in all glioma population and the HGG population." (PMID 33996602, 2021). "The glioma patients with amplified/deleted DR3 or amplified CIITA had worse OS compared with wild-type glioma patients." (PMID 33996602, 2021). "Survival analysis indicated that the CNVs of DR3 and CIITA significantly decreased the OS of glioma patients." (PMID 33996602, 2021). "The GASC score was positively correlated with PD-1, PD-L1, PD-L2, TL1A, TIM3, Galactin-9, CTLA-4, CD80, CD86, CD155, LAG3, and CIITA in all glioma population and the HGG population." (PMID 33996602, 2021). "The study has shown that glioma induces chronic inflammation in microglia and activates Toll-like receptor 2 (TLR2), triggering downstream MAPK/ERK signaling, and responses associated to loss of histone H3 acetylation at CIITA promoters." (PMID 35711434, 2022). "This upregulation is correlated with CIITA inhibition, contributing to glioma immune evasion." (PMID 35711434, 2022). "We also found that the CNVs of DR3 and CIITA were higher in the high-GASC group, and the methylation level of THY1 was lower in the high-GASC group, which could be a potential treatment target for glioma, particularly in HGG." (PMID 33996602, 2021). "Other CIITA-induced, non-MHC-related changes in RNA expression were found in the four tested GB cell lines (the GL261 murine glioma cell line and three human cell lines, U87, GM2, and GM3)." (PMID 39594630, 2024).
leukemia (5 papers, 2004 to 2023). A malignant (clonal) hematologic disorder, involving hematopoietic stem cells and characterized by the presence of primitive or atypical myeloid or lymphoid cells in the bone marrow and the blood. "This indicated that the loss in expression of MHC II was caused by the absence of CIITA, which was epigenetically regulated by CpG island hypermethylation of the CIITApIV promoter in leukemia HL-60 cells." (PMID 25815463, 2015). "To determine whether methylation of CIITA-PIV might be a feature of primary leukaemia, we carried out COBRA analyses using DNA from a group of AML specimens." (PMID 14970863, 2004). "The aim of the present study was to explore the effect of epigenetic modification of class II transactivator (CIITA) methylation on histocompatibility complex (MHC) class II expression and the immune evasion of leukemia HL-60 cells." (PMID 25815463, 2015). "In the present study, leukemia HL-60 cells were treated with the HDACi 5-aza-2′-deoxycytidine (5-Aza-CdR) and/or the DNMTi suberoylanilide hydroxamic acid (SAHA) and then stimulated by IFN-γ to explore their effect on CIITA methylation and the resulting MHC class II expression." (PMID 25815463, 2015).
multiple myeloma (5 papers, 2004 to 2023). "As discussed in Section 5, 2DDR production by myeloma cells and the consequent activation of CIITA in osteocytes are also partially responsible for the elevated SOST, the gene encoding sclerostin, expression in bones bearing myeloma tumors." (PMID 37174109, 2023). "In this regard, myeloma cells produce 2-deoxy-D-ribose (2DDR), which activates the major histocompatibility complex class II transactivator (CIITA) in osteocytes." (PMID 37174109, 2023). "The study has unmasked that 2-deoxyD-ribose derived from myeloma cells promoted the expression of major histocompatibility complex class II transactivator (CIITA) in osteocytes through the STAT1/IRF1 signaling pathway." (PMID 37860014, 2023). "Here the authors report an interaction between malignant plasma cells and osteocytes in multiple myeloma and show that the osteocyte-expressed major histocompatibility complex class II transactivator (CIITA) contributes to myeloma-induced bone lesions." (PMID 35760800, 2022). "Using patient samples, knockout mice, and in vitro cultures, this study demonstrates that osteocyte-expressed CIITA promotes bone destruction in multiple myeloma." (PMID 35760800, 2022). "Most of the cell lines derived from multiple myeloma showed constitutive expression of HLA-DR, which correlated with CIITA-PIV expression." (PMID 14970863, 2004). "However, similar to inhibiting osteocyte apoptosis, blockade of CIITA signaling only partially prevented myeloma-induced RANKL upregulation in osteocytes." (PMID 37174109, 2023). "In multiple myeloma, one may postulate that tumor cell-secreted 2DDR upregulates CIITA expression in myeloid cells and increases osteoclast differentiation through activation of the c-fms/RANKL signaling." (PMID 35760800, 2022). "Nonetheless, CIITA-PIII, which normally directs constitutive MHC class II expression in B-cells, remained suppressed in all myeloma cell lines." (PMID 14970863, 2004). "By contrast, most cell lines of B-cell lineage, including multiple myeloma, show no CIITA-PIV methylation; two (TOM1 and RPMI8226) showed slight methylation." (PMID 14970863, 2004).
rheumatoid arthritis (5 papers, 2014 to 2024). A chronic, systemic autoimmune disorder characterized by inflammation in the synovial membranes and articular surfaces. "Interestingly, transgenic mice constitutively expressing CIITA in joints via the collagen type II (CII) promoter exhibit a strong rheumatoid arthritis (RA)-like phenotype." (PMID 32075058, 2020).
acute myeloid leukaemia (4 papers, 2004 to 2025). "A strong downregulation of CIITA has been reported in blasts from acute myeloid leukemia (AML) relapse cases following allogeneic transplantation of hematopoietic cells." (PMID 33499042, 2021). "CIITA is a regulator of the major histocompatibility complex (MHC) class II gene expression, whose depletion was previously reported in a relapse of acute myeloid leukemia." (PMID 40842820, 2025). "In acute myeloid leukaemia (AML), the CtBP complex transcriptionally represses MHC‐II genes, while the E3 ubiquitin ligase complex component FBXO11 promotes degradation of CIITA." (PMID 40673641, 2025). "Furthermore, methylation of CIITA-PIV was detected in seven of 32 primary acute myeloid leukaemia specimens, indicating that epigenetic alteration is not a cell line-specific phenomenon." (PMID 14970863, 2004).
COVID-19 (4 papers, 2022 to 2025). A disease caused by infection with severe acute respiratory syndrome coronavirus 2. "Although the association between HLA class II and COVID-19 has been uncovered in many previous studies, our study revealed that the molecular interplay between HLA class II and CIITA/CD74 is a key marker underlying the severity of COVID-19." (PMID 40163554, 2025). "Although many studies have focused on the association between HLA class II and COVID-19, our results suggest that the interplay between HLA class II and its regulator and/or target genes (e.g., CIITA and CD74) may play a crucial role in COVID-19 severity." (PMID 40163554, 2025). "Indeed, macrophages in the Post-COVID-19 group showed upregulated class II MHC transactivator encoding CIITA and MHC-II genes." (PMID 39994453, 2025). "Our results suggest that not only HLA class II but also its molecular interplay with CIITA/CD74 may be a key marker for uncovering the mechanism underlying COVID-19 severity." (PMID 40163554, 2025). "The proposed computational network biology strategy revealed the molecular interplay between HLA class II and the identified COVID-19 markers CIITA/CD74 as a COVID-19 severity sepcific marker in the Japanese population." (PMID 40163554, 2025). "Our strategy revealed COVID-19 severe specific molecular interplays between HLA class II and CIITA/CD74, those cannot be revealed by the single gene-based existing studies." (PMID 40163554, 2025). "Subnetwork 1 Subnetwork 1 consists of 25 genes, where only CIITA is the COVID-19 marker." (PMID 40163554, 2025). "Furthermore, the molecular interplay between HLA class II and the COVID-19 marker CIITA was observed in only severe samples." (PMID 40163554, 2025). "This implies that HLA class II and CIITA are crucial markers for understanding COVID-19 severity." (PMID 40163554, 2025). "For example, increased expressions of IL10, IL1R2 mRNA and decreased expression of CD74 and CIITA mRNA were described in monocytes of progressive COVID-19 patients compared with stable patients suggesting the acquisition of a regulatory phenotype by myeloid cells." (PMID 36389738, 2022). "In particular, the identified network comprising HLA class II, CIITA, and CD74 likely played a role in COVID-19 severity, i.e., it was demonstrated that the antiviral activities of CIITA and CD74 protect against coronaviruses." (PMID 40163554, 2025). "Our analysis suggests the gene network between HLA class II, CIITA, and CD74 as a COVID-19 severity specific molecular marker." (PMID 40163554, 2025). "Our findings from computational network biology analysis suggest that suppression and activation of the molecular interplay between HLA class II, CIITA, and CD74 provide crucial clues to uncover the mechanisms of COVID-19 severity." (PMID 40163554, 2025). "Only CIITA, a master regulator of MHC class II genes, was differentially expressed and down-regulated in the COVID-19(+) PU group compared to the COVID-19(-) PU controls." (PMID 37026002, 2023). "CD74, CIITA, CD3D and IL7R were downregulated in critically ill COVID-19 patients in accordance with the occurrence of altered monocyte and T lymphocyte responses." (PMID 36389738, 2022). "Based on our results and the literature, we suggest that controlling the molecular interplay in Subnetwork 1 (i.e., the interplay between HLA class II, CIITA, and CD74) and the enriched pathways provides crucial clinical insights into the mechanism of COVID-19 severity." (PMID 40163554, 2025). "Our results suggest that the suppression or activation (or both) of the interplay between HLA class II, CIITA, and CD74 may provide crucial clinical insights for understanding the mechanism of COVID-19 severity." (PMID 40163554, 2025).
COVID-19 (continued). "In contrast to COVID-19(+) TV, highly expressed in the COVID-19(-) PU control group included MHC class II antigen processing (HLA-DRB3/4, HLA-DPB1, HLA-DRA, CIITA, and CD74), mast cell degranulation (TPSAB1/B2), B cell activation (CXCL13, BLNK, IL-6) and histone modification (USP21, HIST1H4E)." (PMID 37026002, 2023). "Furthermore, the interplay between HLA class II, CIITA, and CD74 may play a key role in the severity of COVID-19." (PMID 40163554, 2025).
Hodgkins lymphoma (4 papers, 2012 to 2023). A heterogeneous group of malignant lymphoid neoplasms of B-cell origin characterized histologically by the presence of Hodgkin and Reed-Sternberg (HRS) cells in the vast majority of cases. "The depth of the RNA-seq data we analyzed is comparable to that in a work identifying recurrent rearrangements of CIITA in Hodgkin lymphoma cell lines." (PMID 26158411, 2015).
pancreatic cancers (4 papers, 2021 to 2024). "To generate HLA-matched MHC-II+ cell lines for these studies, we transduced the KRASG12V+ cell lines NCI-H2444 and DAN-G, derived from human lung and pancreatic cancers, respectively, with CIITA and a construct encoding HLA-DRB5*01:01 with a truncated CD34 reporter gene." (PMID 36512410, 2023). "Tissue microarrays showed uniform low levels of CIITA protein in pancreatic cancers, with focal expression." (PMID 38915093, 2024). "in a human pancreatic cancer cell line of ductal origin (PANC-1) revealed CIITA promoter hypermethylation and low MHC-II expression, even after stimulation with IFN-γ." (PMID 38915093, 2024). "In lung and pancreas cancers, such CIITA/MHC-II-expressing accessory antigen presenting cells can lead to tumor rejection in animal models." (PMID 38201622, 2023). "They suggested that similar to its effect in lung and pancreas tumors, CIITA restoration could act as a therapeutic vaccination strategy in GB." (PMID 38201622, 2023).
asthma (3 papers, 2016 to 2022). "CIITA//rs12932187 and rs11074938 were found to be susceptibility markers of nasal passages inflammation in asthma patients in a Japanese population." (PMID 26833430, 2016). "Moreover, single nucleotide polymorphisms (SNPs) in class II major histocompatibility complex transactivator (CIITA) gene are associated with the development of nasal polyps in asthma patients." (PMID 36118895, 2022).
bladder cancer (3 papers, 2015 to 2023). "In vivo and in vitro EZH2 inhibition in bladder cancer significantly upregulates CIITA levels and tsMHC-II and the efficacy of therapy in vivo is wholly dependent on adaptive immunity." (PMID 37565053, 2023). "Next, we examined the mutations in these genes in bladder cancer and found that the mutation frequency of PTGER4 was the highest, reaching 9%, with amplification mutations as the main mutation; it was followed by RUNX1, IL7, and CIITA, with mutation frequencies of 6, 5, and 5%, respectively." (PMID 32655621, 2020).
breast tumor (3 papers, 2012 to 2025). "Collectively, the data reveal that CIITA expression is linked to specific mutational patterns and the enrichment of pro-tumorigenic signaling pathways, suggesting a broader role for CIITA in influencing the genomic evolution of breast tumors." (PMID 40861816, 2025). "CIITA-high breast tumors exhibited enhanced expression of antigen processing/presentation, co-stimulatory molecules, and immune effector genes, suggesting an expanded immunoregulatory role beyond MHC-II control." (PMID 40861816, 2025). "Our data uncover an overlooked functional interplay between CIITA expression profiles and breast tumor immune phenotypes." (PMID 40861816, 2025). "CIITA overexpression defines an immune-activating transcriptome in breast tumors." (PMID 40861816, 2025). "Taken together, these data suggest that in the LUAD, LUSC and breast tumors, changes in the expression of NLRC5, CIITA, IFNG as well as hypermethylation may play a role in the repression of HLA." (PMID 39358601, 2024). "The same was true for CIITA and IFNG in LUAD and LUSC tumors, but not ER+ breast tumors." (PMID 39358601, 2024).
colitis (3 papers, 2014 to 2025). Inflammation of the colon. "We next examined whether exacerbated colitis in pIV−/− K14 CIITA Tg mice correlates with the loss of inducible MHCII expression by IECs." (PMID 24489792, 2014). "Expression of CIITA in T cells enhances Th2-type immunity, as shown by in vivo studies where transgenic mice expressing CIITA (CIITA-tg mice) had increased susceptibility to oxazolone-induced colitis, an experimental model of Th2 mediated intestinal inflammation." (PMID 25071778, 2014). "In summary, the cellular and molecular mediators of intestinal inflammation in colitic pIV−/− K14 CIITA Tg mice display similarities to those in IBD, underlining the physiological relevance of the applied colitis model." (PMID 24489792, 2014). "Collectively, these results confirm that exacerbated colitis in pIV−/− K14 CIITA Tg mice correlates with the inability of IECs to express MHCII." (PMID 24489792, 2014). "To evaluate whether IFN-γ-induced epithelial MHCII expression protects against colitis we administered neutralizing anti-IFN-γ mAb to pIV+/− K14 CIITA Tg mice 11 days after initial anti-IL-10R treatment to avoid interference with T cell polarization." (PMID 24489792, 2014). "For example, IEC-Bmal1−/− mice demonstrated the significant downregulation of CIITA, a master regulator of MHC class II expression, and it would be pertinent to explore the consequences of this finding with the T cell transfer model of colitis, where MHC II expression is related to colitis severity." (PMID 40822350, 2025).
combined immunodeficiency (3 papers, 2012 to 2025). A broad classification of inherited disorders presenting at birth that affect both the cell-mediated and humoral aspects of the immune response. "Genetic studies of patients with combined immunodeficiency (CID) with predominant CD4 cell deficiency have revealed mutations in genes encoding regulatory factors of the expression of MHC class II molecules such as CIITA, RFXANK, RFX5 or RFXAP." (PMID 25205547, 2014).
diabetes (3 papers, 2019 to 2024). "Additionally, the expression of HLA-DRB1 is also predictive of type 2 diabetes, as is the expression of CIITA and another HLA-DRB1 TF, RFX5, which determine susceptibility to type 2 diabetes mellitus." (PMID 35627314, 2022).
lung adenocarcinoma (3 papers, 2021 to 2025). A carcinoma that arises from the lung and is characterized by the presence of malignant glandular epithelial cells. "Also in lung adenocarcinoma, enforced expression of CIITA increases T cell infiltration and sensitivity to anti-PD-1 therapy." (PMID 33763372, 2021). "Zhang and collaborators (2021) have identified seven N6-methyladenosine-related immune prognostic genes (i.e., PSMD10P1, DIDO1, ABCA5, CIITA, PRC1, ZWILCH, and ANLN) for lung adenocarcinoma (LUAD)." (PMID 37189849, 2023).
lymphopenia (3 papers, 2014 to 2022). Reduction in the number of lymphocytes. "Here, we had used two different methods to induce CD4+ T cell-lymphopenia in mice; one by genetic deficiency of CIITA, the other by treatment with depleting antibody." (PMID 24466045, 2014). "CD4+ T cell-lymphopenia was either induced by anti-CD4 antibody-mediated cell depletion or by genetic deficiency of the major histocompatibility (MHC) class II transactivator (CIITA) in CIITA−/− mice." (PMID 24466045, 2014). "For examples, monocyte alterations (CD74, CIITA mRNA), lymphopenia (CD3, IL7R mRNA), increased anti-inflammatory response (IL10, IL1RN mRNA), altered IFN response (OAS2, IFNG mRNA) were observed." (PMID 36389738, 2022). "Isolated CD4 lymphopenia has been described with MHC Class II deficiency (RFXANK, CIITA, RFXAP) and hypomorphic RAG variants." (PMID 31572360, 2019). "To confirm that the observed impairment of virus control in CIITA−/− mice was indeed caused by CD4+ T cell-lymphopenia and not by some other effect mediated by CIITA deficiency, we infected wild-type C57BL/6 mice that had been depleted of CD4+ T cells with anti-CD4 antibody (GK1.5)." (PMID 24466045, 2014).